DNMT3B (DNA methyltransferase 3 beta)
Diseases named in the same sentence as DNMT3B in open-access papers (continued):
Sharing a sentence is not in itself a finding about the gene and the disease.
seminoma (11 papers, 2012 to 2025). A radiosensitive malignant germ cell tumor found in the testis (especially undescended), and extragonadal sites (anterior mediastinum and pineal gland). "In parallel, DNMT3B-driven de novo methylation silences seminoma-associated genes and epigenetically fixes the EC state." (PMID 26226633, 2015). "Patients with seminomas showing focal DNMT3B expression are at increased risk of relapse, and should be followed up carefully." (PMID 22394436, 2012). "DNMT3A was expressed in 3% (2/79) of seminomas and 36% (37/102) of synovial sarcomas, while DNMT3B was expressed in 33% (27/79) of seminomas and 5% (5/102) of synovial sarcomas." (PMID 38541782, 2024). "The seminoma to EC transition is accompanied by upregulation of the de novo DNA methyltransferase DNMT3B, resulting in a strong increase in DNA methylation levels." (PMID 27283990, 2016). "Under in vitro differentiating conditons both, the parental and SOX2-deficient TCam-2 cells downregulated pluripotency/seminoma markers OCT3/4, TFAP2C, PRDM14 and PRAME, while SOX2 and DNMT3B expression remained low." (PMID 27283990, 2016). "In these somatic microenvironments, TCam-2 cells upregulate EC-markers SOX2, CD30, DNMT3B/L and downregulate seminoma markers SOX17, cKIT and PRDM1." (PMID 26226633, 2015). "Another study of childhood GCTs demonstrated DNA hypermethylation in YSTs compared with seminomas, coincident with higher levels of expression of the DNA methyltransferase, DNMT3B." (PMID 25303610, 2015). "During xenograft experiments, where seminoma-like TCam-2 cells transit to an embryonal carcinoma-like state DNMT3B and DNMT3L where strongly upregulated, which correlated to increasing 5-methylcytosine levels." (PMID 24386123, 2013). "In this study, we examined the expression of DNMT3B protein in seminomas and explored the possibility of using it for prognostication." (PMID 22394436, 2012). "In the present study, we found, using immunohistochemistry, that seminomas were separable into two groups on the basis of DNMT3B protein expression: focal DNMT3B expression with widely scattered nuclear reactivity, and absence of such expression." (PMID 22394436, 2012). "Patients with seminomas showing DNMT3B expression had a significantly lower relapse-free survival rate than patients whose tumours lacked this feature (P = 0.0464)." (PMID 22394436, 2012). "On the basis of these findings, we considered a seminoma to be positive for (focal) DNMT3B expression when one or more tumour cells per 50 high-power fields showed strong nuclear immunoreactivity equivalent to that of embryonal carcinoma." (PMID 22394436, 2012). "According to earlier publications, each histologic subtype has different gene signatures identified by transcriptional profiling: seminomas have overexpressed spermatogenesis-associated genes like PRAME, MAGEA4 and SPAG1 while NSGCTs have overexpressed regulatory genes such as DNMT3B and SOX2." (PMID 40011822, 2025). "The incidence of DNMT3B expression was significantly higher in stage III seminomas (100%) than in stage I (35.7%) or stage II (38.5%) seminomas (P = 0.011), suggesting that such expression may reflect tumour aggressiveness." (PMID 22394436, 2012). "Therefore, we analysed the correlation between DNMT3B expression and various clinicopathological parameters in stage I seminomas." (PMID 22394436, 2012). "In contrast to embryonal carcinomas, most seminomas were completely immunonegative for DNMT3B." (PMID 22394436, 2012). "Focal DNMT3B expression may reflect the potential for differentiation to embryonal carcinomas and other non-seminomatous TGCTs in a proportion of tumour cells in stage I seminoma." (PMID 22394436, 2012). "We found that DPPA3, AK3L1, DNMT3B and NODAL are hypermethylated at analyzed loci in seminomas and parental TCam-2 compared to TCam-2 in vivo 6w and the EC samples." (PMID 26226633, 2015).
seminoma (continued). "For seminoma, this included LZTS1; for EC, DNMT3B, GAL and GPC4; for CHC CGA; and for YSTs AFP, APOA2, BMP2, VTN and OTX2." (PMID 25303610, 2015). "Among them, GDF3, NODAL, LEFTY1 /2, GAL, DPPA3, SOX2, DNMT3B /L, DPPA5, BCAT1, FGF2, PRDM14, ZIC3 and FZD7, while seminoma markers SOX17, cKIT and PRAME were downregulated." (PMID 26226633, 2015). "The incidence of focal DNMT3B expression was higher in stage III seminomas (5/5, 100%) than in stage I (25/70, 35.7%) or stage II (5/13, 38.5%) seminomas (P = 0.011)." (PMID 22394436, 2012). "Thus, immunohistochemistry for DNMT3B, which can be performed on the formalin-fixed, paraffin-embedded tissue specimens prepared for routine pathological diagnosis, may be clinically useful for prognostication of stage I seminomas after prospective validation." (PMID 22394436, 2012). "In seminomas, expression of DNMT3A or DNMT3B was at a low level, as previously reported." (PMID 38541782, 2024). "Patients with seminomas showing focal DNMT3B expression were frequently diagnosed at a higher stage, and had a poorer outcome, than patients with seminomas lacking such expression." (PMID 22394436, 2012). "The relapse-free survival rate of patients with seminomas showing DNMT3B expression was significantly lower than that of patients with seminomas lacking expression (P = 0.0464)." (PMID 22394436, 2012). "Immunohistochemical examination of DNMT3B was performed in 88 cases of seminoma, 35 (39.8%) of which showed widely scattered nuclear immunoreactivity for DNMT3B, and 53 (60.2%) of which were completely negative." (PMID 22394436, 2012). "22,23 Moreover, seminomas showing DNMT3B expression tended to relapse later than non-seminomatous TGCTs." (PMID 22394436, 2012). "Furthermore, there were no significant histological differences between seminomas with focal DNMT3B expression and those lacking it." (PMID 22394436, 2012). "Expression of typical seminoma markers (PRDM1/BLIMP1, SOX17, PRAME, TFAP2C) was also detectable in TCam-2-ΔSOX2/FOXA2 tumor tissues, in contrast to EC reprogramming factors (GDF3, DPPA3, DNMT3B, GAL), which could only be detected in 2102EP in vivo or reprogrammed TCam-2 cells." (PMID 31130628, 2019). "We stratified the TCGA dataset of 156 samples into a seminoma expression signature (SOX17, PRAME, PRDM1 positive; SOX2, DNMT3B, GAL negative) and an EC expression signature (SOX2, DNMT3B, GAL positive; SOX17, PRAME, PRDM1 negative)." (PMID 32418994, 2020). "However, this current study could not observe signs of a seminoma‐to‐EC‐transition, since putative driver genes (NODAL, DNMT3B, DPPA3, and GAL) were rather downregulated upon co‐culture of TCam‐2 cells with TM components compared with TCam‐2 mono‐cultures." (PMID 35811571, 2022).
Burkitt lymphoma (10 papers, 2017 to 2025). A rare form of malignant mature B-cell non-Hodgkin lymphoma. "Similar findings were documented in T-ALL and Burkitt’s lymphoma, where DNMT3B KD and low doses of NA led to a reduction in the number of cells in S-phase, while higher NA concentrations resulted in cell death." (PMID 40241199, 2025). "Shedding light on how MYC controls DNA methylation in T-ALL and Burkitt lymphoma, we recently reported that MYC causes the overexpression of DNMT3B, maintaining specific 5mC and thus gene expression patterns which are important for tumor maintenance." (PMID 31266538, 2019). "Here, we report that in T-ALL and Burkitt’s lymphoma MYC directly caused the overexpression of both DNMT1 and DNMT3B." (PMID 29100357, 2017). "Knock-down of endogenous MYC in human T-ALL and Burkitt’s lymphoma cell lines supports above findings, indicating that DNMT3B overexpression directly depends on high levels of MYC." (PMID 29100357, 2017). "Furthermore, DNA methylation-mediated repression of LMP1 expression in EBV-superinfected Burkitt lymphoma cell lines in vitro is initiated by the DNMT3B de novo methyltransferase and maintained by the DNMT1/UHRF1 maintenance methylation complex." (PMID 38620028, 2024). "DNMT1 and DNMT3B show MYC-dependent overexpression in Burkitt’s lymphoma (BL)." (PMID 35463343, 2022). "Similarly, we previously reported that in T-ALL and Burkitt lymphoma MYC directly controls the overexpression of DNMT3B for tumor maintenance, maintaining specific 5mC and thus gene expression patterns." (PMID 31266538, 2019). "It remains to be seen whether DNMT1 or DNMT3B overexpression is also associated with poor clinical outcome in T-ALL and Burkitt’s lymphoma." (PMID 29100357, 2017). "Hence, shRNA-mediated knock-down of endogenous MYC in human T-ALL and Burkitt’s lymphoma cell lines downregulated DNMT3B expression." (PMID 29100357, 2017). "Further examination of the underlying regulatory mechanism in T-ALL and Burkitt’s lymphoma revealed a direct correlation of DNMT1 and DNMT3B expression with high MYC levels, which led us to assess whether transcriptional regulation is MYC-dependent." (PMID 29100357, 2017). "Approximately 85% of Burkitt lymphoma (BL) patients display DNMT3B overexpression, which contributes to DNA methylation in conjunction with DNMT1." (PMID 40299416, 2025). "Taken together, DNMT1 and DNMT3B expression exhibited a correlation to MYC levels in both mouse T-ALL and human Burkitt’s lymphoma models." (PMID 29100357, 2017). "In both T-ALL and Burkitt’s lymphoma-like cells, treatment with 20ng/mL DOX for 1 and 2 days quickly abrogated MYC transcription; DNMT3B showed a decrease of mRNA followed by the corresponding protein." (PMID 29100357, 2017). "In combination with the promoter binding assay, the expression analysis provides evidence for a direct transcriptional of regulation DNMT3B by MYC in human T-ALL and Burkitt’s lymphoma." (PMID 29100357, 2017). "Based on our expression profiling, we conclude that DNMT1 and DNMT3B are consistently overexpressed in MYC-driven T-ALL and Burkitt’s lymphoma cell lines, while DNMT3A is overexpressed in human T-ALL cell lines only." (PMID 29100357, 2017). "We identified canonical E-box sequences in close proximity to the MYC enrichment peak near the transcription start site (TSS) of DNMT1 and DNMT3B in both T-ALL, and Burkitt’s lymphoma-like cells." (PMID 29100357, 2017). "Subsequent ChIP analysis revealed that MYC occupies sites within the DNMT1 and DNMT3B regulatory regions, suggesting a direct transcriptional regulation in mouse T-ALL and human Burkitt’s lymphoma-like cells." (PMID 29100357, 2017). "Taken together, clinical specimens resembled our data from mouse and human cell line models in regard to DNMT1 and DNMT3B overexpression in T-ALL and Burkitt’s lymphoma." (PMID 29100357, 2017).
Burkitt lymphoma (continued). "In summary, the genomic location analysis together with expression profiling indicates that MYC directly binds to DNMT1 and DNMT3B in T-ALL and Burkitt’s lymphoma, thereby establishing both DNMTs as direct transcriptional targets of the MYC oncoprotein." (PMID 29100357, 2017). "Both T-ALL (Jurkat and HPB-ALL) and Burkitt’s lymphoma (CA46 and Raji) cell lines showed significantly increased DNMT3B mRNA (3.18- to 8.82-fold, respectively, P<0.001) and protein expression in comparison to non-malignant spleen and B-cells, respectively." (PMID 29100357, 2017). "To determine whether DNMT3B overexpression in T-ALL and Burkitt’s lymphoma cells is MYC-dependent, we took advantage of the tetracycline-regulated c-MYC allele in mouse T-ALL (EμSRα-tTA;tet-o-MYC) as well as in a human Burkitt’s lymphoma-like cell line model (P493-6)." (PMID 29100357, 2017). "Overexpression of DNMT1 and DNMT3B has been observed in Burkitt lymphoma (BL) tumour samples, independent of Epstein–Barr virus (EBV) status." (PMID 41297313, 2025). "Similarly, high expression of DNMT3B and DNMT3A suppressed expression of miR-29 through methylation modification and induced disease progression in Burkitt lymphoma." (PMID 35129056, 2022). "By utilizing a tetracycline-regulated MYC transgene in a mouse T-ALL (EμSRα-tTA;tet-o-MYC) and human Burkitt’s lymphoma (P493-6) model, we demonstrated that DNMT1 and DNMT3B expression depend on high MYC levels, and that their transcription decreased upon MYC-inactivation." (PMID 29100357, 2017). "Hence, our finding that MYC directly increases transcription of DNMT3B in T-ALL and Burkitt’s lymphoma reveals a novel mechanism of deregulation in cancer." (PMID 29100357, 2017). "To determine whether DNMT1 and DNMT3B transcription in T-ALL and Burkitt’s lymphoma-like cells is directly regulated by oncogenic MYC, we performed chromatin immunoprecipitation (ChIP) analysis measuring MYC binding to the genomic loci of DNMT1, DNMT3A and DNMT3B." (PMID 29100357, 2017). "In consent with our findings, miR-29b has been reported to have a negative correlation with DNMT3B in Burkitt lymphoma cells, indicating that miR-29b overexpression could decrease the DNMT3B expression, and in turn, miR-29b was inhibited by the DNMT3B in a DNA methylation-dependent manner." (PMID 33177241, 2020). "To determine whether DNMT3B overexpression levels in human B- and T-cell lymphoma cell lines depend on high levels of endogenous MYC, we analyzed a panel of human T-cell lymphoma and Burkitt’s lymphoma cell lines before and upon knock-down of MYC via tetracycline-inducible shRNA." (PMID 29100357, 2017). "To unravel the role of DNA methyltransferases (DNMTs) in MYC-driven hematopoietic malignancies, we performed expression profiling for DNMT1, DNMT3A and DNMT3B comparing MYC-driven T-ALL and Burkitt’s lymphoma cells to non-malignant control cells." (PMID 29100357, 2017).
embryonal carcinoma (10 papers, 2012 to 2024). A non-seminomatous malignant germ cell tumor characterized by the presence of large germ cells with abundant cytoplasm resembling epithelial cells, geographic necrosis, high mitotic activity, and pseudoglandular and pseudopapillary structures formation. "In a previous study of embryonal carcinoma, high expression of the pluripotency-associated DNA methyltransferase 3B (DNMT3B) was associated with sensitivity to 5-Aza." (PMID 26497383, 2015). "In turn, DNMT3A, along with DNMT3B, functions as a de novo methyltransferase that plays important roles in normal development especially during early embryogenesis, as well as in embryonic carcinoma cells." (PMID 31527824, 2019). "All three samples of embryonal carcinoma used as positive controls showed diffuse and strong immunoreactivity for DNMT3B." (PMID 22394436, 2012). "DNA Methyltransferase 3 Beta (DNMT3B) encodes DNA Methyltransferase, which is essential for methylation modification and embryonal development, and DNMT3B PSI values were observed to be significantly elevated in embryonal carcinoma." (PMID 36713456, 2022). "Interestingly, embryonal carcinomas display high levels of DNMT3B and DNMT3L." (PMID 23967156, 2013). "The effectiveness of 5-azacytidine is particularly noted in cases with elevated DNMT3B expression, suggesting its potential utility in managing TGCT, especially the highly aggressive non-seminomatous type, embryonal carcinoma, known for its high DNMT3B enzyme levels." (PMID 38791003, 2024).
multiple myeloma (10 papers, 2019 to 2025). "Employing two different targeting approaches, genetic depletion and pharmacological inhibition using the DNMT3B selective inhibitor NA, we observed strong anti-myeloma effects, with a strong reduction in cell proliferation and clear induction of apoptosis." (PMID 40241199, 2025). "In vitro transfection of U266 and RPMI 8226 cells with a miR29b mimic downregulates the PI3K/AKT pathway and DNMT3B expression, restores proteasome subunit levels, and promotes myeloma cell killing by bone marrow CD8+ T cells from MM patients." (PMID 38654298, 2024). "This loop regulates DNMT3B expression, given that high exogenous levels of miR29b in myeloma cells also downregulate DNMT3B and restore the expression of proteasome subunits." (PMID 38654298, 2024). "For example, piRNA-823 promotes the progression of multiple myeloma by regulating the activity of DNMT3B." (PMID 35354120, 2022). "Myeloma cells cocultured with G-MDSCs induce DNMT3B expression, and antagomir-823 transfection reverses this effect in myeloma cells." (PMID 34199285, 2021). "Because piRNA-823 is directly related to DNA methyltransferase 3A (DNMT3A) and 3B (DNMT3B) in myeloma cells, piRNA-823 inhibition using a piRNA-823 antagomir (antagomir-823) was shown to result in significant decreases in DNMT3A and DNMT3B expression." (PMID 34199285, 2021). "Moreover, the enhanced anti-myeloma effects were also validated in XG-2 DNMT3B KD cells and in the murine 5T33MM model, for which the primary tumor cells (5T33MMvv) were again found much more sensitive to NA treatment than the BMSC." (PMID 40241199, 2025). "Moreover, we found a significant increase in DNMT3B levels in human myeloma cell lines (HMCLs) compared to primary MM cells (p < 0.001) and normal plasma cells (PCs; p < 0.0001)." (PMID 40241199, 2025). "Moreover, NA was found to resensitize Bz and Mel resistant cells, increase the anti-clonogenic capacity of Bz and Mel and enhance the anti-myeloma activity of Bz in DNMT3B depleted cells and in the syngeneic murine 5T33MM model." (PMID 40241199, 2025). "In multiple myeloma, it interacts with DNMT3B and leads to the aberrant DNA methylation." (PMID 38060527, 2023). "A study showed that in multiple myeloma, up-regulation of piRNA-823 could promote the expression of DNMT3B and increase the tumorigenic potential of multiple myeloma stem cells." (PMID 35354120, 2022). "We used the same assay to assess whether CD28 engagement influences levels of miR29b and its target DNMT3B in U266 and RPMI 8226 myeloma cells." (PMID 38654298, 2024). "To determine whether the regulation of miR29b and DNMT3B levels by CD28 involved activation of the PI3K/AKT pathway, we simultaneously exposed U266 and RPMI 8226 myeloma cells to CD28 stimulation and PI3K inhibition with the PI3K inhibitors LY294002 and buparlisib." (PMID 38654298, 2024).
nasopharyngeal carcinoma (10 papers, 2013 to 2024). A carcinoma arising from the nasopharyngeal epithelium. "LMP1 up-regulates DNMT1, DNMT3A, and DNMT3B in EBV-associated nasopharyngeal carcinoma (latency II)." (PMID 32841292, 2020). "DNMT3B was observed to express highly after exposure to irradiation and involvement in radioresistance of nasopharyngeal carcinoma (NPC)." (PMID 33681204, 2021). "Additionally, DNMT3B has been reported to contribute in chemotherapy resistance and promotes radio-resistance in nasopharyngeal carcinoma." (PMID 33233545, 2020).
glioblastoma (9 papers, 2017 to 2025). The most malignant astrocytic tumor (WHO grade IV). "A previous study showed that Dnmt1, Dnmt3a, and Dnmt3b can regulate the methylation status of BIRC5 in glioblastoma multiforme." (PMID 35664300, 2022). "In contrast, aberrant expression of DNMTs, for example, high expression of DNMT1 and DNMT3B and low expression of DNMT3A, has been reported in glioblastoma." (PMID 34214250, 2022). "In glioblastoma (GBM), NSUN2, DNMT3B, NSUN5, TRDMT1, ALKBH1, and HNRNPC were selected." (PMID 40565233, 2025).